SPTLC2 (serine palmitoyltransferase long chain base subunit 2)
Description:
Component of the serine palmitoyltransferase multisubunit enzyme (SPT) that catalyzes the initial and rate-limiting step in sphingolipid biosynthesis by condensing L-serine and activated acyl-CoA (most commonly palmitoyl-CoA) to form long-chain bases. The SPT complex is composed of SPTLC1, SPTLC2 or SPTLC3 and SPTSSA or SPTSSB. Within this complex, the heterodimer consisting of SPTLC1 and SPTLC2/SPTLC3 forms the catalytic core. The composition of the serine palmitoyltransferase (SPT) complex determines the substrate preference. The SPTLC1-SPTLC2-SPTSSA complex shows a strong preference for C16-CoA substrate, while the SPTLC1-SPTLC3-SPTSSA isozyme uses both C14-CoA and C16-CoA as substrates, with a slight preference for C14-CoA. The SPTLC1-SPTLC2-SPTSSB complex shows a strong preference for C18-CoA substrate, while the SPTLC1-SPTLC3-SPTSSB isozyme displays an ability to use a broader range of acyl-CoAs, without apparent preference. Crucial for adipogenesis (By similarity).
Synonyms: LCB2a; KIAA0526; LCB2; hLCB2a; HSN1C; NSAN1C; SPT2
Tractability: Small molecule: a structure with a bound ligand is known; a high-quality ligand is known. Antibody: UniProt predicts a signal peptide or a membrane-spanning region; the Human Protein Atlas places it where antibodies can reach. PROTAC: ubiquitination databases record sites on it; its protein half-life has been measured; a small molecule that binds it is known.
Target class: Enzyme; Transferase
Gene: Protein-coding gene on chromosome 14 (77,505,997 to 77,616,672, reverse strand). Ensembl gene ENSG00000100596.
Subcellular location: Endoplasmic reticulum membrane
Subcellular location (Human Protein Atlas): Plasma membrane; Cell Junctions
Pathways (Reactome):
Metabolism: Sphingolipid de novo biosynthesis
Gene Ontology:
Molecular function: protein binding; serine C-palmitoyltransferase activity; pyridoxal phosphate binding; transferase activity
Biological process: ceramide biosynthetic process; glycosphingolipid biosynthetic process; positive regulation of lipophagy; sphingolipid biosynthetic process; sphingomyelin biosynthetic process; sphingosine biosynthetic process; adipose tissue development; sphingolipid metabolic process
Cellular component: cytoplasmic side of endoplasmic reticulum membrane; serine palmitoyltransferase complex; endoplasmic reticulum membrane
Genetic constraint (gnomAD): Loss-of-function variants: 21 observed, 61.19 expected, observed/expected ratio (o/e) 0.34, 90% interval 0.24 to 0.49. The upper end of that interval is the gene's LOEUF score, 0.49, which puts it in group 2 of 6, group 1 being the genes least tolerant of losing a copy. Missense variants: 494 observed, 701.57 expected, observed/expected ratio (o/e) 0.7, 90% interval 0.65 to 0.76. Synonymous variants: 253 observed, 254 expected, observed/expected ratio (o/e) 1, 90% interval 0.9 to 1.11.
Gene-disease validity (ClinGen):
ClinGen rates the evidence that SPTLC2 causes each of these diseases.
neuropathy, hereditary sensory and autonomic, type 1C (autosomal dominant): Definitive.
amyotrophic lateral sclerosis (autosomal dominant): Strong. Amyotrophic lateral sclerosis (ALS) is a neurodegenerative disease characterized by progressive muscular paralysis reflecting degeneration of motor neurons in the primary motor cortex, corticospinal tracts, brainstem and spinal cord.
Homologues: Orthologues: chimpanzee SPTLC2 (100% identical), macaque SPTLC2 (98% identical), dog SPTLC2 (97% identical), pig SPTLC2 (97% identical), mouse Sptlc2 (96% identical), guinea pig SPTLC2 (96% identical), rat Sptlc2 (95% identical), rabbit SPTLC2 (93% identical), tropical clawed frog sptlc2 (81% identical), zebrafish sptlc2a (78% identical), zebrafish sptlc2b (74% identical). Paralogues in human: SPTLC3 (69% identical), ALAS1 (25% identical), SPTLC1 (24% identical), GCAT (23% identical), ALAS2 (22% identical).